SLC18A1 (solute carrier family 18 member A1)
Description:
[Isoform 1]: Electrogenic antiporter that exchanges one cationic monoamine with two intravesicular protons across the membrane of secretory and synaptic vesicles. Uses the electrochemical proton gradient established by the V-type proton-pump ATPase to accumulate high concentrations of monoamines inside the vesicles prior to their release via exocytosis. Transports catecholamines and indolamines with higher affinity for serotonin. Regulates the transvesicular monoaminergic gradient that determines the quantal size. Mediates presynaptic monoaminergic vesicle transport in the amygdala and prefrontal brain regions related with emotion processing in response to environmental stimuli. [Isoform 2]: Unable to uptake serotonin.
Synonyms: VAT1; VMAT1; CGAT
Tractability: Small molecule: a structure with a bound ligand is known; it belongs to a druggable protein family. Antibody: UniProt predicts a signal peptide or a membrane-spanning region. PROTAC: a small molecule that binds it is known.
Target class: Electrochemical transporter; SLC18 family of vesicular amine transporters; Transporter; SLC superfamily of solute carriers
Gene: Protein-coding gene on chromosome 8 (20,144,855 to 20,183,206, reverse strand). Ensembl gene ENSG00000036565.
Subcellular location: Cytoplasmic vesicle, secretory vesicle membrane; Cytoplasmic vesicle, secretory vesicle, synaptic vesicle membrane; Cytoplasmic vesicle, secretory vesicle membrane (Isoform 1); Endoplasmic reticulum membrane (Isoform 2)
Gene Ontology:
Molecular function: monoamine:proton antiporter activity; monoamine transmembrane transporter activity; serotonin:sodium:chloride symporter activity; transmembrane transporter activity
Biological process: serotonin uptake; aminergic neurotransmitter loading into synaptic vesicle; establishment of localization in cell; neurotransmitter transport; organic hydroxy compound transport; proton transmembrane transport; transmembrane transport
Cellular component: endoplasmic reticulum membrane; synaptic vesicle membrane; terminal bouton; synapse; transport vesicle membrane
Genetic constraint (gnomAD): Loss-of-function variants: 61 observed, 50.69 expected, observed/expected ratio (o/e) 1.2, 90% interval 0.98 to 1.49. The synonymous counts are far from expectation, so gnomAD's model fits this gene poorly and the ratio says little. Missense variants: 899 observed, 666.62 expected, observed/expected ratio (o/e) 1.35, 90% interval 1.28 to 1.42. Synonymous variants: 316 observed, 247.27 expected, observed/expected ratio (o/e) 1.28, 90% interval 1.16 to 1.4.
Homologues: Orthologues: chimpanzee SLC18A1 (99% identical), macaque SLC18A1 (96% identical), guinea pig SLC18A1 (88% identical), dog SLC18A1 (85% identical), pig SLC18A1 (84% identical), rat Slc18a1 (83% identical), rabbit SLC18A1 (83% identical), mouse Slc18a1 (82% identical), zebrafish SLC18A1 (62% identical), tropical clawed frog slc18a1 (60% identical), Drosophila melanogaster Vmat (51% identical), Caenorhabditis elegans cat-1 (45% identical), and 2 more. Paralogues in human: SLC18A2 (62% identical), SLC18A3 (36% identical), SLC18B1 (21% identical).
Diseases named in the same sentence as SLC18A1 in open-access papers:
SLC18A1 is named in the same sentence as 30 diseases in open-access papers, as found by Europe PMC text mining. Sharing a sentence is not in itself a finding about the gene and the disease. The quoted sentences say what the papers report.
Anxiety (6 papers, 2013 to 2025). Intense feelings of nervousness, tension, or panic often arise in response to interpersonal stresses. "The Thr136Ile variant in SLC18A1 affects anxiety, generally associated with personality traits, such as neuroticism." (PMID 30283697, 2018). "On the other hand, the missence variation Thr136Ile in the VMAT1/SLC18A1 gene was found to be associated with anxiety-related personality traits and anxiety has been shown to be associated with obesity or BMI." (PMID 23554917, 2013). "However, the missense variation Thr136Ile in the VMAT1/SLC18A1 gene has been characterized as associated with anxiety-related personality traits, and according to the Harmonizome 3.0 database, Slc18a1 is associated with the functioning of the sympathetic nervous system." (PMID 40806189, 2025). "Thus, the Thr136Ile variant of the SLC18A1 gene might contribute to the quantitative differences of anxiety as a human‐unique personality trait." (PMID 30283697, 2018). "Since Thr136Ile affects the anxiety‐related personality traits and is linked to the anxiety or depressive phenotypes, the evolution from Asn to Thr at the 136th site of SLC18A1 might have led to more anxious human minds through positive selection." (PMID 30283697, 2018). "Downregulation of Slc18a1, Cacna1s, and Htr3a gene expression may be aimed at suppressing the manifestation of anxiety-related traits in ISIAH rats." (PMID 40806189, 2025). "In particular, SLC18A1 (vesicular monoamine transporter 1; VMAT1) gene has a human‐unique variant (rs1390938, Thr136Ile), which is associated with bipolar disorders and/or the anxiety‐related personality traits." (PMID 30283697, 2018). "Additionally, other studies have shown that genes SLC18A1 and LINC02022 are related to lipid measurement (triglycerides and cholesterol), which are further recognized for their connections to depression, anxiety, and stress-related disorders by recent studies." (PMID 39999171, 2025).
depression (4 papers, 2019 to 2025). "Genetic variation in the VMAT-1 gene (SLC18A1) has been implicated in the activity of neural circuits associated with emotion, it plays an important role in brain structural changes in patients with depression." (PMID 36059987, 2022).
schizophrenia (4 papers, 2006 to 2025). A major psychotic disorder characterized by abnormalities in the perception or expression of reality. "KDM5C gene silencing leads to down-regulation of SCN2A, CACNA1B; CACNA1H; SCL4A3, SLC18A1, and SLC6A12, All of these KDM5C target genes have been linked to neurological disorders such as epilepsy, autism or schizophrenia." (PMID 39948613, 2025).
neuroblastoma (3 papers, 2019 to 2025). Neuroblastoma (NB) is the most common solid, extracranial childhood tumor. "Overall, we found that downregulation of 7 genes (Crb1, Lrrc9, Rcn1, Rtl1, Shisa3, Six6, St18) and upregulation of 2 genes (C1ql3, Slc18A1), are strongly predictive of favorable neuroblastoma outcome, consistent with delayed tumor development in Th-MYCN/Casp2−/− mice." (PMID 30670683, 2019).
Obesity (2 papers, 2013). Accumulation of substantial excess body fat. "Interestingly, a third group of genes (CPE, NPY5R, DRD3, TAS2R38, SLC18A1, G6PC3, NPY1R, and VLDLR) was highly associated with both neurological and obesity concepts." (PMID 23544116, 2013).
Parkinson disease (2 papers, 2017 to 2020). A progressive degenerative disorder of the central nervous system characterized by loss of dopamine producing neurons in the substantia nigra and the presence of Lewy bodies in the substantia nigra and locus coeruleus. "Parkinson’s disease is a pathway specifically associated to diseases of the central nervous system, NDUFB5 and SLC18A1 are enriched in this pathway." (PMID 29170526, 2017).
Hypertension (1 paper, 2025). The presence of chronic increased pressure in the systemic arterial system. "Despite the fact that a population-based study using randomly selected polymorphisms in the SLC18A1 gene showed its significant association with hypertension, the VMAT1/SLC18A1 gene has not been associated with the development of hypertension to date." (PMID 40806189, 2025).
mood disorder (1 paper, 2018). A cognitive disorder a disturbance in which the person's mood is hypothesized to be the main underlying feature. "Moreover, genome wide and candidate gene studies identified SLC18A1 as one potential pleiotropic gene overlapped between mood disorders and cardiometabolic diseases (Amare, Schubert, Klingler‐Hoffmann, Cohen‐Woods, & Baune, 2017)." (PMID 29998543, 2018).
neuroendocrine tumors (1 paper, 2011). "Eight genes (CHGA, CPE, ENO2, INSM1, PTPRN2, SERPINA10, and SLC18A1/2) that have been previously identified as markers of neuroendocrine tumors were confirmed in this study to be altered." (PMID 21853033, 2011).
tumor (9 papers, 2003 to 2024). "The expression of many classifier genes of the pseudohypoxic cluster (i.e., Epas1, Slc18A1/2, Ndufa4l2, Vegfa) increased with the size of the rat tumors suggesting that they play an important role in tumor progression, but not necessarily in tumor initiation." (PMID 33401758, 2021).
psychiatric disorder (4 papers, 2018 to 2025). A disorder characterized by behavioral and/or psychological abnormalities, often accompanied by physical symptoms. "Moreover, Slc18a1 has been implicated in the development and treatment of psychiatric disorders, further suggesting a functional role of mir-411-5p in this context." (PMID 32848656, 2020). "The present study detects three psychiatric disorder‐relevant genes (CLSTN2, FAT1, and SLC18A1) that have been under positive selection during the human evolution." (PMID 30283697, 2018).
SLC18A1 also shares sentences with these, for which no sentence is quoted: alcohol dependence (3 papers); pheochromocytoma (3); autism (2); bipolar disorder (2); alcoholism (1); autoimmune gastritis (1); bipolar I disorder (1); breast tumor (1); cancer (1); Cognitive impairment (1); diseases of the central nervous system (1); epilepsy (1); glioma (1); memory impairment (1); neuroendocrine carcinoma (1); neurological disorders (1); ovarian carcinoma (1); paraganglioma (1); stress-related disorder (1).